TLR4 (toll like receptor 4)
Diseases named in the same sentence as TLR4 in open-access papers (continued):
Sharing a sentence is not in itself a finding about the gene and the disease.
Obesity (continued). "Another study shows that in the hypothalamus of the diet-induced obesity mouse model, activation of TLR4 by palmitic acid elicits inflammatory responses that result in the functional resistance to leptin." (PMID 34385421, 2021). "Obesity is associated with increased inflammation in adipose tissue, with monocyte chemoattractant protein 1 (MCP-1), IL-6, toll-like receptor 4 (TLR4), and TNFα elevated in adipose tissue of obese relative to lean individuals." (PMID 34149621, 2021). "By contrast, other studies reported increase TLR2 and TLR4 gene expression especially in the adipose tissue of diet-induced obesity in mice." (PMID 34083551, 2021). "TLR4 triggers metabolic inflammation and insulin resistance during obesity by upregulating the transcription of proinflammatory genes and activating proinflammatory kinases JNK, IKK, and p38." (PMID 34445300, 2021). "TLR4 is a well-known activator of innate immune responses against pathogens and has recently been shown to mediate obesity-induced cardiac inflammation, glucose metabolic derangement and injury." (PMID 33762947, 2021). "It has also been shown that skeletal muscle cells from individuals with obesity and T2D express more TLR4 than lean controls and show indications of elevated NFkB/IkB-signalling." (PMID 34930972, 2021). "Diabetes, obesity and coronary artery disease are some of the conditions in which increased TLR4 expression has been reported." (PMID 34030677, 2021). "Studies on HFD-induced obesity have shown that myocardial damage is significantly alleviated by TLR4 depletion." (PMID 33762947, 2021). "The transcription factor, nuclear factor kappa light chain enhancer of activated B cells (NF-κB), and Toll-like receptor 4 (TLR4) have been identified as important mediators propagating the effects of obesity on inflammation." (PMID 33498671, 2021). "During lipid overnutrition, circulating free fatty acids, whose levels are commonly increased in obesity, accumulate in the liver as fat storage, and at the same time, in concert with LPS, trigger TLR4/NF-κB pathway." (PMID 33265944, 2020). "The mediators of the brain innate immune system, including TLR4, IκB kinase-β/NF-κB (IKKβ/NF-κB), ER stress and autophagy, are involved in obesity-related inflammatory signaling." (PMID 32760236, 2020). "The increase in expression of the TLR4 gene, reported in differentiating adipocytes in db/db mice suggests that this gene is critical during obesity development processes." (PMID 32485856, 2020). "Cytokine profiles in obesity have been observed to be similar to lipopolysaccharide (LPS)-induced TLR4 pathways." (PMID 32403975, 2020). "Molecular docking analysis further identified three binding sites for spermidine in the TLR4 protein, indicating a link between TLR4 signaling and spermidine-mediated anti-obesity effects." (PMID 33151120, 2020). "The complex cellular makeup of adipose tissue raises an intriguing question regarding the role of TLR4 in promoting obesity-induced inflammation and adipose tissue dysfunction." (PMID 32403975, 2020). "It has been demonstrated that TLR4 plays a key role in the progression from hepatic steatosis to NASH in mice with obesity-induced NAFLD." (PMID 32472368, 2020). "Previous studies have also indicated a role for TLR4 in the development of adipose tissue fibrosis and insulin resistance in obesity." (PMID 32403975, 2020). "In this study, we found that TLR4/AP-1 siRNA transfection alleviated systemic and hepatic inflammation and further ameliorated high-fat diet-induced obesity and insulin resistance in mice." (PMID 33013197, 2020). "The deletion, the knockdown or the pharmacological inhibition of TLR4 protects mice from obesity, inflammation, and leptin resistance." (PMID 32576879, 2020). "Obesity is thought to lead to increased Toll-like receptor 4 (TLR4) stimulation in adipocytes via a variety of ligands, and expression of both IL-6 and MCP1 by adipocytes can be induced by inflammation." (PMID 32603641, 2020).
Obesity (continued). "Our former work demonstrated that TLR4/MyD88/CaMKII signaling pathway contributed to obesity-induced ventricular electrical remodeling." (PMID 32733242, 2020). "Obesity releases free fatty acids (FFA) that trigger the Toll-like receptor 4 (TLR4) signaling pathway, resulting in the activation of the nuclear factor-kappaB (NF-κB), a master transcription regulator in the production of pro-inflammatory cytokines, TNF-α." (PMID 32751794, 2020). "Increased circulating LPS levels activate the pattern recognition receptor toll-like receptor 4 (TLR4) and trigger proinflammatory and oxidative cascades that contribute to the development of metabolic imbalances observed in obesity and T2DM." (PMID 32012784, 2020). "Using similar approaches with various loss-of-function TLR-4 mouse models, four other laboratories described essential roles for TLR-4 in obesity and/or insulin resistance." (PMID 33072120, 2020). "Among the TLR family members, TLR2 and TLR4 are considered important regulators of metabolic inflammation during the development of obesity and related comorbidities." (PMID 31936430, 2020). "In our series of young adults, obesity increased fasting TLR2 surface expression but decreased that of TLR4." (PMID 31936430, 2020). "Our results indicated that TLR4/AP-1 siRNA transfection alleviated high-fat diet-induced systemic and hepatic inflammation, obesity, and insulin resistance in mice." (PMID 33013197, 2020). "LPS plays an important role in inducing inflammatory response of obesity-related metabolic diseases by activating the TLR4/NF-κB signaling pathway." (PMID 32724821, 2020). "In this line, our previous study demonstrated that a high-fat diet induced a marked upregulation of TLR4 in an in vivo model of early obesity." (PMID 32624568, 2020). "Given our recent findings of the role of TLR4 in myeloid biasing in obesity, we next investigated the role of TLR4 in adipocyte generated inflammatory responses to SFAs and lipopolysaccharides." (PMID 32403975, 2020). "It is critical to investigate the cell type-specific responses of TLR4 to ligands such as palmitate to better understand TLR4’s role in SFA-mediated inflammation during obesity." (PMID 32403975, 2020). "Knocking out TLR2 and TLR4 can prevent diet-induced obesity and insulin resistance through inflammatory signaling pathways." (PMID 31952471, 2020). "LPS produced by gram-negative bacteria or dietary fatty acids have shown to activate TLR4 and the inflammatory response after a reduced integrity of the intestinal barrier in obesity models." (PMID 32098336, 2020). "Of note, TLR4 expression is enhanced significantly in adipose tissue macrophages during obesity and TLR4/TLR2 expression was found to be significantly higher in M1 compared to M2 macrophages." (PMID 32806763, 2020). "miR-107 contributes in inflammation and obesity in a Toll-like receptor 4/myeloid differentiation primary response 88 manner (TLR4/MYD88) in the activated macrophages located in the adipose tissue; it also is known to be a lipid-modulated miRNA." (PMID 32366215, 2020). "More recent studies have mechanistically corroborated these findings, linking microbiota-related inflammatory changes during HFD-induced obesity to Toll-like receptor 4 (TLR4) signaling and a resultant increase in plasma levels of LPS." (PMID 32326175, 2020). "Adipocytes express TLR4; once these TLR4 are activated, it causes a pro-inflammatory state in adipose tissue via release of pro-inflammatory cytokine, thus initiating a potent immune response, which in turn may be involved in the developments of obesity and cardiometabolic syndrome." (PMID 32708841, 2020). "This is further substantiated by observations of increased expression of TLR4 in skeletal muscle tissue in subjects with obesity and T2D." (PMID 32295104, 2020). "Enhanced β-cell damage in obesity was correlated with an increased percentage of inflammatory macrophages expressing galectin 3 and TLR4 in the islets of TG mice." (PMID 32117058, 2020).
Obesity (continued). "LPS and SCFAs affect obesity through spurring specific cascades, including LPS-dependent TLR4 pathway and SCFAs-dependent GPRs pathway in both adipose and the liver tissues." (PMID 32439940, 2020). "Although some prior studies have suggested a role for TLR4 in promoting FFA-induced inflammation during obesity, many of the findings in recent literature are contradictory." (PMID 32403975, 2020). "Previous studies showed female TLR4−/− mice to have increased obesity but to be partially protected against HFD induced insulin resistance, possibly owing to reduced expression of inflammatory genes in the liver." (PMID 32151087, 2020). "Enhanced TLR4 signaling is increased in muscle, visceral fat tissue, and liver under obesity, which is responsible for obesity inflammation, obesity-related insulin resistance, and liver diseases." (PMID 31582899, 2019). "TLR4 is the most widely described PRR in obesity-induced chronic inflammation and development of metabolic diseases." (PMID 31582899, 2019). "Collectively, these data strongly demonstrate the implication of brain TLR4 signaling in the pathogenesis of obesity, inflammation and insulin resistance." (PMID 30906281, 2019). "The use of anti-HMGB1 neutralizing antibody effectively reduce HFD-induced weight gain and liver inflammation in mice, suggesting that TLR4 is likely a key therapeutic target for dyslipidemia and obesity." (PMID 31507457, 2019). "One of the mechanisms involved in the onset of low-grade inflammation in vitro and in vivo models of obesity is mediated by toll-like receptor 4 (TLR4) stimulated by dietary SFA." (PMID 31035535, 2019). "HMGB1 has been shown to mediate TLR4 activation in human adipocytes, which are also elevated in obesity." (PMID 31582899, 2019). "There were studies that indicated the association of TLR with body adiposity and obesity; a TLR- 4 variant was associated with adiposity of the body and liver, and TLR-4 deficiency protected obesity induced by diets with high saturated fat." (PMID 30709060, 2019). "The main signalling pathways involved in OA inflammation, which are associated with obesity, are protein tyrosine phosphatase 1B (PTP1B) and TLR4 or DAP12." (PMID 31781260, 2019). "In obesity, TLR4 is considered as the main target for saturated fatty acids in the hypothalamus and peripheral tissues that triggers inflammatory response and endoplasmic reticulum stress promoting whole body insulin resistance." (PMID 30906281, 2019). "Circulating levels of FAs are significantly higher in obese compared with lean individuals, which results in increased TLR4 signaling in obesity and inflammation." (PMID 31582899, 2019). "It has become more evident that the gut microbiota is altered in obesity, leading to activation of the LPS-toll-like receptor 4 (TLR4) axis and modulation of the intestinal barrier integrity." (PMID 31500176, 2019). "By comparing HFD‐induced changes in systemic and local joint inflammation in animal models that modulate TLR4 signaling positively and negatively, we provide new insight into how TLR4‐dependent pathways are activated and regulated in obesity, aging, and OA." (PMID 31044181, 2019). "The TLR4 recognizes lipid ligands and plays an important role in non-infectious inflammatory diseases such as insulin resistance, obesity, and NAFLD." (PMID 31035535, 2019). "The implication of TLR4 in obesity was further evidenced by studies reporting that TLR4 knockdown or its pharmacological inhibition, protect mice from diet induced inflammation and insulin resistance." (PMID 30906281, 2019). "All these results suggest that TLR4 plays an irreplaceable role in regulating obesity-related metabolic diseases." (PMID 31582899, 2019). "A previous study also indicated that TLR4 is a new target for chemoprevention of hepatocellular carcinoma in obesity and steatohepatitis." (PMID 31582899, 2019). "In obesity, the interactions between adipocytes and macrophages aggravate adipose inflammation through TLR4." (PMID 31582899, 2019).
Obesity (continued). "Among the different members of the TLR family, TLR4 is considered as a major contributor of obesity-induced inflammation and insulin resistance." (PMID 30906281, 2019). "We observed that HFD increased TLR4 expression in the IFP and synovium of WT mice, consistent with obesity‐induced upregulation of TLR4‐dependent signaling in joint tissues." (PMID 31044181, 2019). "Gram-negative bacteria-derived LPS has been defined as the primum movens in the development of obesity and its related metabolic diseases through binding with toll-line receptor 4 (TLR4) and subsequently activating CD14." (PMID 31374958, 2019). "In conclusion, the present study suggests that a compensatory genetic interaction between TLR2 and TLR4 contributes to the prenatal LPS stimulation-induced hyperlipidemia and lipid overload-induced obesity." (PMID 31507457, 2019). "Prior studies indicate that the innate immune receptor toll‐like receptor 4 (TLR4) mediates obesity‐induced metabolic inflammation and cartilage catabolism via recognition of damage‐associated molecular patterns and is increased with aging in OA joints." (PMID 31044181, 2019). "The LPS-dependent TLR4/CD14 pathway is one of the pivotal signals of the development of obesity resulting from intestinal dysbacteriosis." (PMID 31374958, 2019). "Development of liver and adipose tissue insulin resistance has been related to LPS-dependent activation of Toll-like receptor 4 (TLR4) in macrophages, independently of obesity." (PMID 31096592, 2019). "As TLR4 dependent signaling is increased in obesity PI3Ks would presumably limit pro-inflammatory responses through various mechanisms including the promotion of M2 responses." (PMID 31497027, 2019). "In therapeutic animal studies, TAK-242 (a TLR4 inhibitor) attenuates insulin resistance in muscle cells and the adverse neural effects of diet-induced obesity." (PMID 31582899, 2019). "Different experimental and clinical researches identified the TLR4 signaling pathways activated by resistin as the molecular mechanism that links insulin resistance and obesity." (PMID 31772701, 2019). "These indicate that SC-LCBs can control obesity through inhibition of LPS-dependent TLR4/CD14 signal and activation of SCFAs-mediated GPRs proteins." (PMID 31374958, 2019). "All five markers of obesity-related inflammation in the hippocampus (Il-6, Tnf-α, Cd11c, Tlr4 and Nptx251,52) were down-regulated by ENOblock treatment." (PMID 30679508, 2019). "In particular, clinical and experimental studies have identified resistin as a key hormone linking obesity-induced hypothalamic inflammation and insulin resistance through the activation of TLR4 signaling pathways." (PMID 31582899, 2019). "Data concerning the effect of muscle inflammation on postprandial muscle protein synthesis in people with obesity is largely limited to the toll-like receptor 4 (TLR4) signaling pathway." (PMID 31263701, 2019). "In obesity, in addition to an increased intake of saturated fatty acids, TLR4 and TLR2 expression are increased in the AT, further supporting the role of these receptors in obesity-associated inflammatory signaling." (PMID 32063863, 2019). "Further investigations are needed to clearly decipher regulatory mechanisms involved in hypothalamic resistin/TLR4 signaling in the context of obesity." (PMID 30906281, 2019). "To investigate this possibility, we examined how pharmacological inhibition of TLR4 affects the peripheral and neural outcomes of diet-induced obesity." (PMID 30396359, 2018). "In summary, high concentrations of free fatty acids play an important role in the activation of TLR4/NF-κB/IL-6 inflammatory signaling pathways by promoting the expression of KLF7 in obesity." (PMID 30598636, 2018). "The aim of this study was then to evaluate the influence of T2DM and obesity in the TLR4 pathway of neutrophils from rats." (PMID 30510205, 2018).
Obesity (continued). "We further show that the BM myeloid>lymphoid bias that arises early in obesity depends on BM cell subset-autonomous TLR4." (PMID 29453396, 2018). "TLR4 knockout relieves HFD-induced phosphorylation of IKKβ, JNK, mTOR, and proinflammatory signaling molecules, which can alleviate obesity-associated inflammation." (PMID 30050954, 2018). "The goal of this study is to examine the role of TLR4 signaling in mediating the effects of obesity on microglial activation and adverse neural outcomes." (PMID 30396359, 2018). "The aim of this study was to evaluate the influence of type 2 diabetes and obesity in the TLR4 pathway in rat neutrophils." (PMID 30510205, 2018). "To establish the in vivo role of TLR4 in impaired emergency immune responses in obesity, we compared 5-FU recovery patterns in WT and TLR4-deficient mice." (PMID 29453396, 2018). "Abundance of fatty acids in obesity promotes AT inflammation in a toll-like receptor 4 (TLR4)-dependent manner." (PMID 28891325, 2018). "TLR4 is abundantly expressed in insulin target tissues such as adipose tissue, liver and skeletal muscle and is now accepted as a key player in obesity-induced insulin resistance and T2DM." (PMID 29666152, 2018). "In this context, the TLR4 signaling pathway has been recognized as one of the main triggers in increasing the obesity-induced inflammatory response." (PMID 29601492, 2018). "The connection of TLR4 and lipid metabolism makes TLR4 a potential target to control adipose tissue inflammation and insulin resistance in obesity." (PMID 29922174, 2018). "Our findings support the conclusion that TLR4 contributes to obesity-induced activation of peripheral macrophages and brain microglia." (PMID 30396359, 2018). "The toll-like receptor 4 (TLR4) signaling pathway is acknowledged as one of the main triggers of the obesity-induced inflammatory response." (PMID 29601492, 2018). "Here, the authors show that diet and obesity, as well as low-dose lipopolysaccharide, can alter Toll-like receptor 4 signaling bone marrow cells to skew the myeloid-lymphoid homeostasis in mice." (PMID 29453396, 2018). "Two tightly connected pathways in obesity activate TLR4 through specific ligands and result in the exacerbation of inflammation; elevated free fatty acids (FFA) as well as lipopolysaccharide (LPS)-linked to changes in gut microbiota." (PMID 29426925, 2018). "The use of several different knockout mouse strains, both of TLR4 and CD14, and a variety of mouse diets has complicated our understanding of the role of the TLR4 pathway in the development of obesity." (PMID 30353127, 2018). "The identification of fetuin-A as a physical adapter between TLR4 and dietary saturated fats provides the opportunity to investigate the mechanistic role pathway in obesity-driven BM malfunction." (PMID 29453396, 2018). "Together, these results establish a mechanistic contribution of BM cell-intrinsic TLR4 to obesity-driven BM malfunction and demonstrate the importance of LPS." (PMID 29453396, 2018). "Ageing and obesity synergistically induce diabetes through TLR4, supporting the therapeutic potential of TLR4 inhibition to treat T2D." (PMID 29426925, 2018). "To test the possibility that BM precursor TLR4 regulates BM development in early stages of obesity, we generated chimeras in which WT BM (CD45.1) was mixed with TLR4-deficient BM (CD45.2) and co-engrafted into WT hosts (CD45.1/2)." (PMID 29453396, 2018). "We found that treatment with TAK-242 significantly increased the number of new neurons in dentate gyrus specifically in HFD-fed mice, indicating a protective effect of TLR4 inhibition on obesity-related impairment in neurogenesis." (PMID 30396359, 2018). "One pathway that is particularly important in mediating the effects of obesity in peripheral tissues is toll-like receptor 4 (TLR4) signaling." (PMID 30396359, 2018).